CLDN4 (claudin 4)
Diseases named in the same sentence as CLDN4 in open-access papers (continued):
Sharing a sentence is not in itself a finding about the gene and the disease.
triple-negative breast carcinoma (8 papers, 2016 to 2025). An invasive breast carcinoma which is negative for expression of estrogen receptor (ER), progesterone receptor (PR), and human epidermal growth factor receptor 2 (HER2). "In triple-negative breast cancer, low expression of CLDN4 was found to be accompanied by high expression of TGF-β." (PMID 35418179, 2022). "We have observed that siRNA targeting of PVT1 exon 9 in claudin-low triple negative breast cancer cells resulted in re-expression of claudin 4 protein, and inhibition of migration." (PMID 33801373, 2021). "For example, Abd-Elazeem M.A. and Abd-Elazeem M.A.26 reported high levels of claudin 4 expression in 66.1% of triple-negative breast cancer, particularly in invasive carcinoma, which correlated with the expression of Ki67." (PMID 27021602, 2016). "Furthermore, among triple-negative breast cancer subjects, the "CLDN4-high/LXRβ-high" and "CLDN4-low and/or LXRβ-low" groups appeared to exhibit poor outcomes and relatively favorable prognoses, respectively." (PMID 37059993, 2023). "Consequently, further research into molecular mechanisms regulating CLDN4 expression in triple negative breast cancer is warranted." (PMID 33801373, 2021). "Genomic studies have uncovered a claudin-low subtype of triple-negative breast cancer (TNBC), characterized by reduced expression of CLDN3 (claudin 3), CLDN4 (claudin 4), CLDN7 (claudin 7), and E-cadherin." (PMID 39858010, 2025). "High expression of claudin-4 in primary tumors, and particularly in distant metastases, is a negative prognostic indicator in ER(-) and triple-negative breast cancer patients and is a powerful predictor of survival." (PMID 28881568, 2017).
ulcerative colitis (8 papers, 2016 to 2025). An inflammatory bowel disease involving the mucosal surface of the large intestine and rectum. "We also assessed the expression of claudins Cldn4 and Cldn8 in the colonic mucosa since the expression of Cldn4 has previously been shown to be downregulated in patients with ulcerative colitis." (PMID 38255781, 2024). "In particular, pore-forming claudin-2 expression was upregulated in this disease, whereas claudin-4, 5, 7, and 8 were downregulated in crohn's disease (CD) and ulcerative colitis (UC)." (PMID 36597137, 2023). "Remarkably, claudin-4 and -7 levels are both downregulated in ulcerative colitis." (PMID 40438590, 2025). "Likewise, it is reported that patients with active Crohn's disease or ulcerative colitis and impaired intestinal permeability have decreased expression of occludin as well as claudin 4, 5, 7, and 8, whereas claudin 2 is strongly upregulated." (PMID 32793187, 2020). "Importantly, claudin-4 expression is downregulated in intestinal biopsies of patients with ulcerative colitis, indicating the potential clinical significance of the experimental observations." (PMID 28103316, 2017).
colon carcinoma (7 papers, 2014 to 2023). "The loss of CLDN3 induces Wnt/β-catenin activation in colon cancer, while downregulation of CLDN4 results in E-cadherin loss and increased β-catenin signalling." (PMID 32093760, 2020). "Hypermethylation of CpG islands in the CLDN4 promoter region reduces CLDN4 expression in gastric, bladder, and colon cancers." (PMID 36982569, 2023). "Our approach aimed at evaluation of a selective and targeted cancer gene therapy of claudin-3- and/or claudin-4- expressing colon carcinoma in vitro and in vivo by using translation optimized CPE expressing vector." (PMID 28193196, 2017). "The results showed that the CPE is a gene transfer system and can be considered as an appealing therapeutic agent in colon carcinomas through the targeting of claudin-3 and/or claudin-4 which lead to rapid and impressive tumor cell killing in both in vitro and in vivo conditions." (PMID 34281519, 2021). "This novel approach demonstrates that optCPE gene transfer represents a promising and efficient therapeutic option for a targeted suicide gene therapy of claudin-3 and/or claudin-4 overexpressing colon carcinomas, leading to rapid and effective tumor cell killing in vitro and in vivo." (PMID 28193196, 2017). "By screening of 27 colon carcinoma PDX for claudin-3 and/or -4, the clinical relevance of this approach was further supported, as 20 out of 27 PDX models showed both, claudin-3 and claudin-4 expression, whereas 3 revealed the expression of only claudin-3, suggesting, that binding of CPE can occur." (PMID 28193196, 2017).
lymph node metastasis (7 papers, 2013 to 2025). "Low expression of CLDN4 is associated with advanced T stage, lymph node metastasis, and recurrent status." (PMID 40687428, 2025). "The results showed that CTC counts (HR = 1.3, p < 0.001), Claudin-4 (HR = 4.6, p = 0.008), and lymph node metastasis (HR = 12.9, p = 0.001) were independent prognostic factors for poor prognosis." (PMID 37465316, 2023). "In contrast, there was a correlation between lymph node metastasis and CLDN4 expression in the nodal metastasis foci, which was higher than in the primary lesion." (PMID 32064037, 2020). "Claudin-4 high/claudin-1 low, claudin-4 high/claudin-7 low, and claudin-4 high/claudin-1 low/claudin-7 low types were also significantly correlated with lymph node metastasis, and showed worse survival." (PMID 31861759, 2019). "High CLDN4 levels in PDAC correlates with lymph node metastasis and distant metastasis." (PMID 40687428, 2025). "Comparison of Claudin-4 in patients’ age, lymph node metastasis, and molecular classification." (PMID 37465316, 2023). "Most patients with high Claudin-4 expression had lymph node metastasis (55.6% vs. 15.8%, p < 0.001 vs. without low Claudin-4 expression)." (PMID 37465316, 2023). "CLDN4 expression was not correlated with histological type, histological grade, cancer progression (pT), lymph node metastasis (pN), or stage." (PMID 33172177, 2020).
gastric adenocarcinoma (6 papers, 2008 to 2025). "CLDN-4 has further been identified as one of the markers of gastric adenocarcinoma precursor lesions and found to be expressed in gastric adenocarcinoma." (PMID 35743616, 2022). "Claudin-4 is upregulated in gastric adenocarcinomas, and increased claudin-4 expression is more commonly seen in intestinal-type as opposed to diffuse-type tumors." (PMID 23822740, 2013). "We demonstrated upregulation of claudin-4 in intestinal metaplasia and gastric epithelial dysplasia, which suggests its potential utility as a biomarker in gastric adenocarcinoma precursor lesions." (PMID 23822740, 2013). "Consistently, CLDN4 and CEACAM5 mRNA levels are significantly higher in gastric adenocarcinomas compared to normal gastric samples from the large TCGA and GTEx cohorts, with CLDN4 showing higher expression levels than CEACAM5 in normal tissues." (PMID 40868067, 2025). "In the current study, human gastric adenocarcinoma cells, AGS, constitutively expressing claudin-4 were generated." (PMID 25120725, 2014).
lung adenocarcinoma (6 papers, 2018 to 2025). A carcinoma that arises from the lung and is characterized by the presence of malignant glandular epithelial cells. "The aim of this was study to detect the diagnostic accuracy of the expression of HEG1 and Claudin-4 in distinguishing malignant mesothelioma from lung adenocarcinoma in pleural effusion." (PMID 40091315, 2025). "On the other hand, all cases of benign effusions and all MPM cases had negative Claudin-4 immunoexpression while positive membranous Claudin-4 immunoexpression was found in 94.9% of lung adenocarcinoma cases." (PMID 40091315, 2025). "The aim of this study was to ascertain the diagnostic accuracy (specificity and sensitivity) of HEG1 and Claudin-4 expression in differentiating between lung adenocarcinoma and malignant mesothelioma in pleural effusion cases." (PMID 40091315, 2025). "There was a statistically significant difference in immunoexpression of Claudin-4 between benign effusion and lung adenocarcinoma." (PMID 40091315, 2025). "Comparison between MPM and lung adenocarcinoma regarding IHC staining for Claudin-4 and HEG1." (PMID 40091315, 2025). "They concluded that MPM or RMCs in pleural effusions may be successfully distinguished from lung adenocarcinoma using Claudin-4 IHC." (PMID 40091315, 2025). "Diagnostic performance of IHC staining for Claudin-4 and HEG1 in diagnosis of lung adenocarcinoma." (PMID 40091315, 2025). "On the other hand, a high expression of CLDN-4 decreased the survival rate in lung adenocarcinoma." (PMID 38338691, 2024). "In this present study, our findings indicate that the downregulation of CGN and FOXO1 leads to malignant cell proliferation, cell migration, and altered cell metabolism by upregulating CLDN-2 or CLDN-4 through the MAPK/AMPK pathways in human lung adenocarcinoma A549 cells." (PMID 38338691, 2024). "There was a statistically significant difference in the immunoexpression of Claudin-4 between MPM and lung adenocarcinoma." (PMID 40091315, 2025). "Whereas 37 out of 64 (57.8%) malignant effusion (lung adenocarcinoma, MPM cases) were Claudin-4 positive, all cases of benign effusion with RMCs were Claudin-4 negative." (PMID 40091315, 2025). "For differential diagnosis between MM and lung adenocarcinoma, TTF-1, Napsin A, CEA, claudin 4 (CLDN4), Ber-EP4, and MOC31 are useful markers suggesting lung adenocarcinoma." (PMID 29538329, 2018). "The IMIG guideline has suggested the use of Calretinin, D2–40, WT1, and CK5/6 as mesothelial markers, TTF-1, Napsin-A, Claudin 4, CEA as lung adenocarcinoma markers p40, p63, CK5/6, MOC-31 as squamous cell markers." (PMID 29317712, 2018). "The sensitivity, specificity, and accuracy of MUC4 are comparable to that of previously known markers of lung adenocarcinoma and squamous cell carcinoma, namely CEA, Claudin 4 and better than that of MOC-31." (PMID 29317712, 2018). "In conclusion, in human lung adenocarcinoma, the downregulation of CGN induces malignancy via the upregulation of MEK-dependent CLDN-2 and cell metabolism and cell migration, and the downregulation of FOXO1 induces malignancy via the downregulation of CGN and CLDN-4 and cell proliferation." (PMID 38338691, 2024). "Furthermore, we discovered that the Claudin-4 sensitivity was 94.8%, specificity was 100%, negative predictive value was (92.5%), positive predictive value was (100%), and accuracy was 96.8% when it came to the diagnosis of lung adenocarcinoma." (PMID 40091315, 2025).
asthma (5 papers, 2021 to 2025). "While several TJ proteins, such as ZO-1 and claudin-18, are downregulated in all asthma phenotypes (although in variable extents), claudin-4 overexpression is exclusively found in non-T2 (neutrophilic) asthma." (PMID 34248677, 2021). "Thus, a positive correlation of asthma with systemic IL-10 and organoid expression of Tnf, Cxcl10, Cldn5, Cldn4 in the A group was found." (PMID 38255939, 2024). "Plasma levels of claudin-4 and claudin-5 were reported to be elevated in asthma patients, particularly during exacerbations, and the levels were found to correlate negatively with lung function and positively with total IgE level and the percentage of blood eosinophils." (PMID 33790367, 2021). "Analysis of tight‐junction gene sets revealed the reduced expression of a whole cluster of genes such as OCLN, CLDN3, CLDN4, NRAS, HCLS1, MYH10 in virus‐infected cells from patients with asthma in comparison to the controls." (PMID 39466641, 2025).
glioma (5 papers, 2013 to 2026). A benign or malignant brain and spinal cord tumor that arises from glial cells (astrocytes, oligodendrocytes, ependymal cells). "The heightened expression of CLDN4 is linked to larger glioma sizes and this claudin might be a promising biomarker and potential therapeutic target of patients with glioma." (PMID 41399659, 2026). "Moreover, overexpression of CLDN4 is associated with increased tumor sizes in glioma xenograft models." (PMID 41399659, 2026). "Collectively, these findings suggest that CLDN4 holds promise as a valuable biomarker and a potential therapeutic target for glioma treatment." (PMID 41399659, 2026). "In vitro investigations demonstrate that elevated CLDN4 expression significantly enhances glioma cell proliferation and migration." (PMID 41399659, 2026). "In summary, our findings indicated that the TGF-β/CLDN4/TNF-α/NF-κB signal axis plays a key role in the biological progression of glioma." (PMID 35418179, 2022). "We observed that the expression of CLDN4 was highest in GBM patients compared wtih low-grade glioma brain tissues." (PMID 35418179, 2022). "Then Kaplan–Meier analysis was performed by TCGA data set, and it was found that CLDN4 was closely related to the overall survival (OS) in glioma, suggesting the predictive value of CLDN4 in the prognosis of glioma patients." (PMID 35418179, 2022). "Firstly, we found that CLDN4 was highly expressed in high-grade glioma in the Cancer Genome Atlas (TCGA) data set." (PMID 35418179, 2022). "In this study, CLDN4 is a gene related to the progression of glioma which was determined by The Cancer Genome Atlas (TCGA)." (PMID 35418179, 2022). "The tumor-promoting role of the CLDN4/NNAT axis has been further confirmed in glioma organoids." (PMID 41399659, 2026). "Collectively, these results suggest that the TGF-β/CLDN4/TNF-α/NF-κB signaling axis plays a critical role in glioma progression, and its disruption may offer a promising therapeutic strategy for GBM." (PMID 41399659, 2026). "However, compared with normal group, the expression of CLDN4 was significantly increased in glioma group." (PMID 35418179, 2022). "This study aimed to determine whether CLDN4 mediates glioma malignant progression, if so, it would further explore the molecular mechanisms of carcinogenesis." (PMID 35418179, 2022). "IHC staining was used to detect the expression of CLDN4 in different grades of glioma." (PMID 35418179, 2022). "Specifically, we discovered CLDN4/TNF-α/NF-κB signal axis in glioma for the first time." (PMID 35418179, 2022). "Our results revealed that CLDN4 was significantly upregulated in glioma specimens and cells." (PMID 35418179, 2022). "In addition, combined with previous studies, we first identified that the classic TGF-β signal pathway can regulate the expression of CLDN4 and nuclear translocation in glioma." (PMID 35418179, 2022). "Additionally, CLDN4 influences glioma progression by modulating the NNAT/Wnt signaling pathway." (PMID 41399659, 2026). "In the CGGA data set, CLDN4 was highly expressed in high-grade glioma, compared with WHO grade II glioma." (PMID 35418179, 2022). "Glioma C6 CM did not alter the expression of occludin and claudins 1 and 3 in ReNcells CX, butdecreased the amount of claudin-4." (PMID 23637756, 2013).
hepatocellular carcinoma (5 papers, 2013 to 2025). A malignant tumor that arises from hepatocytes. "For tumors in other locations, such as esophageal carcinoma and hepatocellular carcinoma, a reduced claudin-4 expression was also associated with shortened recurrence-free survival." (PMID 36232536, 2022). "Similarly, palmitoylation at cysteine residues C104/C107 of Claudin 4 (CLDN4) in hepatocellular carcinoma (HCC) stabilizes its lipid raft anchoring by inhibiting clathrin-mediated endocytosis, activating the Notch pathway to drive lenvatinib resistance." (PMID 40977744, 2025).
invasive carcinoma (5 papers, 2005 to 2023). A carcinoma that is not confined to the epithelium, and has spread to the surrounding stroma. "Cells containing HG-PIN in association with invasive carcinoma exhibited strong levels of claudin-4 staining." (PMID 18648369, 2008). "The loss of CLDN4 expression in areas of apocrine metaplasia and in the majority of grade 1 invasive carcinomas also suggests a particular role for this protein in mammary glandular cell differentiation and carcinogenesis." (PMID 15743508, 2005). "In contrast, HG-PIN cells in conjunction with invasive carcinoma displayed strong claudin-4 staining, but AMACR levels were low and PSMA levels were moderate." (PMID 38188015, 2023). "Furthermore, benign glands in the PCa sections were moderate (56%; 14 out of 25) to high (44%; 11 out of 25) for claudin-4 staining and, in some cases, higher than that found in invasive carcinoma cells." (PMID 18648369, 2008). "In considering this relationship, sections containing HG-PIN without associated invasive carcinoma were of moderate intensity for claudin-4 and of low intensity for PSMA and AMACR." (PMID 18648369, 2008). "Initially, 18 sections with HG-PIN without invasive carcinoma were examined for claudin-4 expression." (PMID 18648369, 2008).
metastatic tumors (5 papers, 2008 to 2025). "Most of the metastatic tumours stained positively for claudin-4, with the majority classified as strong or intense and only a minority registering moderate expression." (PMID 18648369, 2008). "That is, EZH2 similarly to other CC markers e.g. CK7, CK19, claudin 4 does not provide major help in distinguishing cholangiocarcinomas from metastatic tumors, but it does seem to be able to differentiate reactive/hamartomatous biliary structures and benign biliary tumors from malignant ones." (PMID 22809481, 2012).
undifferentiated carcinoma (5 papers, 2017 to 2024). A usually aggressive malignant epithelial neoplasm composed of atypical cells which do not display evidence of glandular, squamous, or transitional cell differentiation. "Immunostaining for claudin-4 was positive in 97% of goiters (60/62), 72% of adenomas (42/58), 91% of papillary carcinomas (20/22), and 20% of anaplastic carcinomas (2/10)." (PMID 39458944, 2024). "Significantly, Claudin 4 expression may be useful to distinguish switch/sucrose non-fermentable complex-deficient undifferentiated carcinomas from sarcomas." (PMID 28376864, 2017).
adenoma (4 papers, 2020 to 2024). A neoplasm arising from the epithelium. "Claudin-4 expression was the highest in papillary thyroid carcinoma tissues and was significantly higher than in adenomas and goiters (74.33 vs. 51.87 vs. 47.22, respectively; p < 0.05)." (PMID 39458944, 2024). "Papillary thyroid cancer and thyroid adenoma showed positive expression of claudin-1, while claudin-4 was positive in papillary thyroid cancers, goiters, and adenomas." (PMID 39458944, 2024). "In our study, claudin-4 was expressed in well-differentiated samples, both benign (goiter, adenoma) and malignant (papillary carcinoma)." (PMID 39458944, 2024). "In our cohort, claudin-1 and claudin-4 expression patterns were similar, with nearly uniform positive expression in papillary carcinomas, negative expression in undifferentiated and medullary carcinomas, and varied expression in adenomas." (PMID 39458944, 2024). "When the authors divided the tumors between high-grade IPMNs (including borderline, carcinoma in situ, and invasive cancers) and low-grade IPMNs (adenomas), significantly elevated levels of claudin-4 mRNA were seen in the high-grade group when compared to the IPMN adenomas." (PMID 37627123, 2023). "The situation differed slightly regarding claudin-4, expressed by goiters, adenomas, and PTC but not by MTC and ATC." (PMID 39458944, 2024). "Claudin-4 expression was positive in PTCs, goiters, and adenomas but negative in medullary and anaplastic thyroid cancers." (PMID 39458944, 2024). "There was no statistical difference between the median expression of claudin-4 in goiters and adenomas." (PMID 39458944, 2024). "The expression of claudin-18 was similar to claudin-4, where one of three IPMN adenomas showed negative expressions of claudin-18, while seven of eight IPMN carcinomas strongly expressed claudin-18." (PMID 37627123, 2023).